COL4A3 (collagen type IV alpha 3 chain)
Diseases named in the same sentence as COL4A3 in open-access papers (continued):
Sharing a sentence is not in itself a finding about the gene and the disease.
Alport syndrome (continued). "One patient had familial FSGS, five had Alport syndrome with mutations in COL4A5 (four) and COL4A3 (one), one had PAX2 mutation, one NUP150 mutation and nephrotic range proteinuria, and one a variant in CLCN5 causing Dent Disease." (PMID 39950157, 2025). "In summary, identifying P/LP variants in COL4A3, COL4A4, or COL4A5 during reproductive carrier screening provides an important opportunity for early clinical intervention for Alport syndrome heterozygotes and their families." (PMID 40317772, 2025). "Our study provides important insights into the genetic landscape of Alport syndrome, confirming the central role of COL4A5 variants in X-linked inheritance and the involvement of COL4A3 and COL4A4 genes in autosomal forms." (PMID 40004525, 2025). "The 7 other positive tests included amyloidosis (TTR, N = 3), Alport syndrome (COL4A3, N = 2), polycystic kidney disease (PKD1, N = 1), and susceptibility to end stage renal disease (APOL1, N = 1)." (PMID 40126616, 2025). "Variants in COL4A3 and COL4A4 cause autosomal dominant and recessive Alport syndrome, yet data on their distribution and clinical expression in different populations remain limited." (PMID 40806767, 2025). "Autosomal recessive Alport syndrome (ARAS) is the second most prevalent type, resulting from pathogenic variants in both copies of either the COL4A3 or COL4A4 genes on chromosome 2." (PMID 40790091, 2025). "The focus of this guideline is to describe the current state-of-art in the diagnosis, management, and treatment of the disorders resulting from the genetic defects in COL4A3/4/5 genes including the classical Alport syndrome (AS) (ORPHA 63)." (PMID 39673454, 2025). "Experimental investigations on Alport syndrome typically use collagen, type IV, alpha 3–null (Col4a3-null) mice on the 129 or B6 genetic backgrounds and occasionally F1 hybrids thereof." (PMID 40059824, 2025). "The X-linked form of Alport syndrome is caused by variants in the COL4A5 gene, and the autosomal form is caused by variants in COL4A3 or COL4A4." (PMID 40392259, 2025). "A defect of the α-chains COL4a3/a4/a5 can lead to Alport syndrome which affects the basement membranes of the kidney, inner ear, and eye." (PMID 38997817, 2024). "Pathogenic variants in COL4A3 (HGNC:2204) are recognized to be associated with COL4A-related diseases, commonly referred to as Alport syndrome." (PMID 38790019, 2024). "People with one altered and one normal copy of an autosomal COL4A3 or COL4A4 gene have autosomal dominant (AD) Alport syndrome." (PMID 38745975, 2024). "Subsequent re-analysis of the sequencing data detected the NM_000091.4: c.3182 G>A; p.(Gly1061Asp), variant of uncertain significance (VUS) in COL4A3 (HGNC:2204), a gene associated with recessive and dominant forms of Alport syndrome (MIM 203780 and 104200)." (PMID 38790019, 2024). "Previous studies have identified that autosomal dominant mutations of Col4A3, Col4A4 or Col4A5 are associated with thin basement membrane nephropathy (TBMN), Alport syndrome and other hereditary kidney diseases." (PMID 37323683, 2023). "In Col4a3−/− Alport syndrome mice, the anti-fibrotic effects of anti-microRNA-21 were demonstrated, these protective effects were increased further when combined with ACE inhibitor therapy." (PMID 39429698, 2023). "Bi-allelic variants in COL4A3 and COL4A4 cause autosomal recessive Alport syndrome, characterized by progressive kidney failure, sensorineural hearing loss, and ocular abnormalities." (PMID 36925663, 2023). "More than 1000 mutations have been identified in the COL4A3, COL4A4, and COL4A5 genes leading to a reclassification of Alport syndrome and thin basement membrane nephropathy as type IV collagen nephropathies." (PMID 37180518, 2023). "COL4A3/4/5 genes constitute the largest fraction, implying they are regularly overlooked using clinical Alport syndrome criteria and displaying the existence of phenocopies." (PMID 36100708, 2022).
Alport syndrome (continued). "Many more variants have been reported for COL4A5 than for COL4A3 and COL4A4 because genetic testing has been performed more often for individuals suspected of having X-linked Alport syndrome." (PMID 35602506, 2022). "Monoallelic deleterious variants in COL4A3 and COL4A4 cause autosomal dominant forms of Alport syndrome (AS)." (PMID 36013122, 2022). "The Col4a3 knock out mouse is a well-known as a model of Alport syndrome, characterized by proteinuria and progressive glomerular nephropathy with hyperplasia of GBM." (PMID 35271660, 2022). "Pathogenic variants in COL4A5 usually cause X-linked Alport syndrome (XLAS), whereas those in the COL4A3 or COL4A4 genes are associated with autosomal dominant (AD) or recessive (AR) inheritance." (PMID 35419377, 2022). "Currently, three disease-causing genes, namely collagen type IV alpha 3–5 (COL4A3, COL4A4, and COL4A5), have been associated with the occurrence of Alport syndrome." (PMID 36159970, 2022). "Heterozygous pathogenic COL4A3 and COL4A4 variants affecting Gly (n = 304) in autosomal dominant Alport syndrome were correlated with the risk of haematuria in the UK 100,000 Genomes Project." (PMID 35177655, 2022). "Although a majority of COL4A4 or COL4A3 pathogenic variants have been associated with autosomal recessive Alport syndrome (ARAS), there are also variants associated with autosomal dominant Alport syndrome (ADAS)." (PMID 35842573, 2022). "Its main cause is heterozygous mutations of COL4A3 or COL4A4, which also cause late-onset focal segmental glomerulosclerosis (FSGS) or autosomal dominant Alport syndrome (ADAS)." (PMID 36292665, 2022). "Pathogenic variants in COL4A5 usually cause X-linked Alport syndrome (XLAS), while alterations in COL4A3 and COL4A4 genes are associated with autosomal dominant AS (ADAS) or autosomal recessive AS (ARAS)." (PMID 35419377, 2022). "Mutations in COL4A3, COL4A4, or COL4A5—encoding the α3, α4, or α5 (IV) chains, respectively—cause various diseases, including thin basement membrane nephropathy (TBMN), Alport syndrome (AS), and late-onset focal segmental glomerulosclerosis (FSGS)." (PMID 36292665, 2022). "Mutations of COL4A5 on the X chromosome, as well as mutations of COL4A3 and COL4A4 on chromosome 2, can cause both Alport Syndrome and FIgAN." (PMID 34717572, 2021). "In Col4a3-knockout mice, a model of Alport syndrome with renal fibrosis, renal ACE2 mRNA was repressed and restored to the no/marginal change level by olmesartan." (PMID 33750913, 2021). "Increased laminin deposition in the GBM has been reported in a Col4a3–/– mouse model of Alport syndrome." (PMID 33749661, 2021). "Of the 17 monogenic disorders detected in our study, Alport syndrome due to COL4A5/COL4A3 accounted for one third of all genetic diagnoses." (PMID 34215756, 2021). "We treated 129S1/SvImJ background Col4a3−/− Alport syndrome mice, which have a shorter lifespan than C57BL/6 background Col4a5 G5X Alport syndrome mice, with losartan or metformin alone, or in combination, via drinking water from 4 weeks old." (PMID 33782421, 2021). "Mutations in COL4A5, COL4A3, and COL4A4, the three Alport syndrome genes, have been reported in patients presenting as FSGS." (PMID 31049720, 2020). "Here, we report the protective effect of CG200745 (CG), a novel histone deacetylase inhibitor, on tubulointerstitial fibrosis in Col4a3−/− mice, a murine model of Alport syndrome." (PMID 32098220, 2020). "In conclusion, we reported six XLAS children with heterozygous pathogenic COL4A3 or COL4A4 variants, which accounted for 1% of Alport syndrome." (PMID 30883042, 2019). "Up to 10% of familial FSGS can be explained by autosomal COL4A3/4 mutations; however, COL4A5 mutations leading to X-linked Alport syndrome (XLAS) are much more common." (PMID 30691124, 2019). "The diseases associated with heterozygous mutations in COL4A3 or COL4A4 genes are thin basement membrane nephropathy and autosomal dominant Alport syndrome." (PMID 30883042, 2019).
Alport syndrome (continued). "In this study, among 417 patients diagnosed or suspected of Alport syndrome in our department during 2014–2017, six were identified with pathogenic variants in COL4A5 plus heterozygous pathogenic variants in COL4A3 or COL4A4, which accounted for 1%." (PMID 30883042, 2019). "Here we report the application of newly developed helium ion scanning microscopy (HIM) to examine the glomerulopathy in a Col4a3 mutant/Alport syndrome mouse model." (PMID 28916834, 2017). "Twelve laboratories involved worldwide in mutation testing for Alport syndrome collaborated to submit 754 novel variants (504 COL4A5, 133 COL4A3, 117 COL4A4 variants) to the LOVD databases." (PMID 27627812, 2016). "In renal fibrosis, the regulatory role of αvβ6 has been investigated by using both function-blocking αvβ6 antibodies and the mouse model of Alport syndrome (Col4A3−/− mice) combined with β6 integrin knockout mice." (PMID 27139180, 2016). "Founder mutations were reported in both COL4A3 and COL4A4 in autosomal recessive Alport syndrome and Thin basement membrane nephropathy." (PMID 27627812, 2016). "This study confirmed that COL4A5, and COL4A3 and COL4A4 mutations in Alport syndrome all resulted in end-stage renal failure at the same age." (PMID 27627812, 2016). "Other investigators observed that in a model mimicking the Alport’s syndrome (COL4A3−/− mice), deletion of DDR1 delays renal fibrosis via inhibition of NF-κB, IL-6 and TGF-β signaling." (PMID 26880216, 2016). "We will understand better genotype-phenotype correlations for heterozygous COL4A3 and COL4A4 mutations in Thin basement membrane nephropathy, and any genetic distinctions from variants that cause autosomal dominant Alport syndrome." (PMID 27627812, 2016). "Many fewer DNA variants have been described for the COL4A3 and COL4A4 genes, presumably because autosomal recessive Alport syndrome is less common, and genetic testing is performed infrequently for Thin basement membrane nephropathy." (PMID 27627812, 2016). "Genetic ablation of β6 integrin, in a model of Alport syndrome (Col4A3−/− mice), resulted in similar effects on renal fibrosis." (PMID 27139180, 2016). "Clinical features were compared between individuals with autosomal recessive Alport syndrome caused by COL4A3 or COL4A4 pathogenic mutations and those with X-linked Alport syndrome and COL4A5 mutations." (PMID 27627812, 2016). "This study was designed to investigate sex-phenotype correlations and evaluate the contribution of macrophage infiltration to disease progression using Col4a3 knock out (Col4a3KO) mice, an established genetic model of autosomal recessive Alport syndrome." (PMID 26555339, 2015). "It was discovered that overexpression of COL4A3 or COL4A4 in the embryonic lens results in microphthalmia and cataract, and mutation in COL4A3, COL4A3, and COL4A5 cause Alport syndrome." (PMID 25124159, 2014). "In this in vivo study, COL4A3−/− mice served as a model for progressive renal disease seen in the human Alport syndrome." (PMID 25525413, 2014). "The allele distributions of three polymorphisms already described in previous studies related to Alport syndrome (D326Y in COL4A3 and M1327V and F1644F in COL4A4) were significant for the KC patient cohort." (PMID 20029656, 2009). "Autosomal recessive Alport syndrome (ARAS) accounts for about 15% of affected individuals and arises from mutations in both alleles of COL4A3 or COL4A4, which respectively encode the α3(IV) and α4(IV) chains." (PMID 17912554, 2009).
Alport syndrome (continued). "Of 91,000 pregnant people screened by a commercial laboratory, the observed carrier frequency for a P/LP variant was one in 279 for COL4A3, one in 332 for COL4A4, and one in 3055 for COL4A5, giving an overall carrier rate of one in 144 for any one of the Alport syndrome genes." (PMID 40317772, 2025). "Number of variants in COL4A3, COL4A4, and COL4A5 of Alport syndrome." (PMID 40949880, 2025). "COL4A3, COL4A4, and COL4A5 are predominantly expressed in and critical for maintaining the structural integrity of the glomerular basement membrane, alterations in these genes lead to basement membrane disruption, which is the primary cause of Alport syndrome." (PMID 40351420, 2025). "The three collagen IV genes involved in Alport syndrome are COL4A3, COL4A4, and COL4A5." (PMID 38745975, 2024). "This candidate was effective in reducing kidney fibrosis and improving kidney function to significantly extend the survival of Human Immunodeficiency Virus-Associated Nephropathy Transgenic 26 (HIVAN Tg26) and Collagen Type IV Alpha 3 Chain Null Alport Syndrome (Col4a3-null Alport syndrome) mice." (PMID 39598332, 2024). "At least 22 annotated and 17 nonannotated genes were identified in this region of chromosome 2q36 by querying the UCSC Human Genome Browser, including the COL4A3 and COL4A4 genes, which were associated with the development of Alport syndrome and thin basement membrane disease." (PMID 38202130, 2023). "Mono-allelic variants in COL4A3 and COL4A4 (COL4A3/COL4A4) have been identified in a spectrum of glomerular basement membrane nephropathies, including thin basement membrane nephropathy and autosomal dominant Alport syndrome." (PMID 36925663, 2023). "Patients with FSGS and mutation in COL4A3, A4, or A5 should be classified as patients with Alport syndrome, and we should not use any immunosuppressive therapy because of its apparent ineffectiveness." (PMID 36982595, 2023). "This study examined a Romani cohort for pathogenic variants in the COL4A3, COL4A4, and COL4A5 genes that are affected in Alport syndrome (AS), a common cause of genetic kidney disease, characterized by hematuria, proteinuria, end-stage kidney failure, hearing loss, and eye anomalies." (PMID 36844206, 2023). "Future studies will focus on confirming more closely a genotype-phenotype correlation using proteinuria rather than kidney failure in women with X-linked Alport syndrome and in individuals with heterozygous COL4A3 or COL4A4 pathogenic variants." (PMID 35602506, 2022). "Therefore, depletion of col4a3 or col4a4 in zebrafish is a model of the early stages of Alport syndrome." (PMID 35716957, 2022). "With AR Alport syndrome, two severe variants in COL4A3 or COL4A4 have a more damaging effect than one or none." (PMID 35602506, 2022). "To test how MNP subset dynamics may be influenced by kidney injury we therefore analyzed kidney MNPs isolated from Col4a3−/− mice with Alport syndrome." (PMID 34168267, 2021). "Mutations in COL4A3, COL4A4 and COL4A5 genes lead to Alport syndrome (AS)." (PMID 34508137, 2021). "Mutations of COL4A3 and COL4A4 on chromosome two are also common causes of Alport syndrome." (PMID 34717572, 2021). "Interestingly, COL4A mutations have emerged in patients with CKD beyond Alport syndrome, including FSGS, increasing the relevance of our studies in Col4a3-/- mice." (PMID 34502419, 2021). "Notably, the combination of losartan (125 μg/mL) and low-dose metformin (2.5 mg/mL) increased the survival of Col4a3−/− Alport syndrome mice more than losartan alone." (PMID 33782421, 2021).
Alport syndrome (continued). "Three modes of inheritance exist for AS: X-linked Alport syndrome (XLAS) (mutations involving COL4A5 on the X chromosome), autosomal recessive Alport syndrome (ARAS) (mutations in COL4A3 or COL4A4 on chromosome 2), and autosomal dominant Alport syndrome (ADAS) (mutations in COL4A3 or COL4A4)." (PMID 34858896, 2021). "Alport syndrome (OMIM, X-LINKED, TS1, # 301050; AUTOSOMAL RECESSIVE, TS2, # 203780; AUTOSOMAL DOMINANT, TS1, # 104200) is caused by mutations in COL4A3/4/5 genes, which encode type IV collagen α3/4/5 chains (α3 chain, UniProt Q01955; α4 chain, P53420; α5 chain, P29400)." (PMID 32117450, 2020). "Mutations in the COL4A3 and COL4A4 genes are the cause of autosomal recessive Alport syndrome (ARAS) (OMIM203780), with symptoms similar to those in male XLAS patients and autosomal dominant thin basement membrane disease, with a varying but usually milder phenotype." (PMID 33233744, 2020). "We identified two deleterious nonallelic COL4A3 mutations, one novel and the other previously reported in an Alport syndrome (AS) patient." (PMID 24130771, 2013). "It was previously reported that podocytes are cellular origins of COL4A3, 4 and 5 in developing glomeruli, raising the possibility that podocytes could be a therapeutic target in Alport syndrome." (PMID 22937108, 2012). "However, subsequent whole-exome sequencing revealed a c.3209C > T mutation in the COL4A3 gene, confirming Alport syndrome, while no mutation was detected in the GLA gene." (PMID 41516147, 2025). "However, recent expert consensus guidelines recommend genetic confirmation as essential, defining Alport syndrome more broadly to include all individuals harboring pathogenic variants in COL4A3, COL4A4, or COL4A5, regardless of their clinical presentation." (PMID 40852417, 2025). "Renal damage is the most life-threatening symptom of X-linked Alport syndrome (XLAS), an inherited disease caused by X-linked COL4A5 gene mutations, which cause more than 80% of all Alport syndrome cases (the remaining cases are caused by COL4A3/COL4A4 gene mutations)." (PMID 40075271, 2025). "Variants and mutations in the COL4A3 gene may result in diabetic kidney disease (DKD) in young adults with maturity-onset diabetes, and pathogenic COL4A3 mutations have been identified for Alport syndrome (AS), a progressive inherited nephropathy." (PMID 38926794, 2024). "The diagnosis of Alport syndrome is suspected when an individual has the characteristic clinical features or a family history of Alport syndrome, and it is optimally confirmed by the demonstration of a disease-causing variant in the COL4A5, COL4A3, or COL4A4 genes." (PMID 37895203, 2023). "In the LOVD database, the age at kidney failure was not different for AR and for X-linked Alport syndrome (24.4 ± 7.8 years, n = 237, p = 0.39), and in the case of AR disease, was not different for COL4A3 (23.2 ± 9.3, n = 35, p = 0.45) or COL4A4 (25.4 ± 10.3, n = 26, p = 0.55) variants." (PMID 35602506, 2022). "The relationship is less clear for severe heterozygous COL4A3 or COL4A4 variants in AD Alport syndrome since kidney failure is not common and may be due to coincidental disease." (PMID 35602506, 2022). "Although developed as a model of Alport Syndrome, studies of Col4a3-/- mice may also provide insights into the pathogenesis of a wider spectrum of kidney disease because the Col4a3 gene plays a role in both sporadic and familial FSGS as well as diabetic nephropathy." (PMID 34502419, 2021). "Inheritance of Alport syndrome is X-linked (OMIM301050), autosomal recessive (OMIM 203780), digenic (typically with a pathogenic variant in each of COL4A3 and COL4A4) or autosomal dominant (OMIM 104200, or thin basement membrane nephropathy, due to heterozygous COL4A3 or COL4A4 variants)." (PMID 33854215, 2021).